TULP3 (TUB like protein 3)
Diseases named in the same sentence as TULP3 in open-access papers:
TULP3 is named in the same sentence as 45 diseases in open-access papers, as found by Europe PMC text mining. Sharing a sentence is not in itself a finding about the gene and the disease. The quoted sentences say what the papers report.
colorectal cancer (4 papers, 2019 to 2025). A primary or metastatic malignant neoplasm that affects the colon or rectum. "Importantly, TULP3 was reported as a prognostic marker in colorectal cancer and pancreatic ductal adenocarcinoma." (PMID 31868202, 2020). "Nowadays, most of the studies on TULP3 focus on its effects on tumors and embryonic development in mice, including the fact that TULP3 is highly expressed in patients with abdominal aortic aneurysm, pancreatic cancer, and colorectal cancer, and that it has been shown to promote cancer progression." (PMID 40282234, 2025). "One published study showed that expression levels of TULP3, a protein related to TULP1, were increased in colorectal cancer when compared to adjacent non-tumoral tissue." (PMID 40141211, 2025).
cystic kidney disease (4 papers, 2022 to 2025). A congenital or acquired kidney disorder characterized by the presence of renal cysts. "Altogether, we here show that the loss of Tulp3 causes defects in ciliary function during early zebrafish development that eventually lead to liver fibrosis, cystic kidney disease and scoliosis in adult animals." (PMID 40940409, 2025). "This recessive hypomorphic allele was identified in a forward genetic screen in the mouse that caused rapid cystic renal disease and the analogous mutation in human TULP3, K389I, disrupted ciliary trafficking of ARL13B, GPR161, and INPP5E." (PMID 36276950, 2022). "In mice, Tulp3 mutations disrupt ciliary trafficking leading to abnormal ciliary protein composition, defects in cellular signaling and renal cystic disease." (PMID 36276950, 2022). "In adult Tulp3-deficient zebrafish, we observed fibrocystic disease including liver fibrosis and cystic kidney disease, which mirrors the clinical presentation of affected individuals with deleterious TULP3 mutations." (PMID 35397207, 2022). "TULP3 is a ciliary trafficking protein that links membrane-associated proteins to the intraflagellar transport complex A. In mice, mutations in Tulp3 drive phenotypes consistent with ciliary dysfunction which include renal cystic disease, as part of a ciliopathic spectrum." (PMID 36276950, 2022).
abdominal aortic aneurysm (3 papers, 2020 to 2025). Enlargement and ballooning of the vessel that supplies arterial blood to the abdomen, pelvis and legs. "Additionally, miR-4688 targeting TULP3 promotes the formation of abdominal aortic aneurysms through the STAT3/NEAT1/miR-4688/TULP3 axis." (PMID 40282234, 2025). "Moreover, STAT3 may function as one positive feedback regulator that induces the upregulation of NEAT1 as a competing endogenous RNAs (ceRNA) that then facilitates abdominal aortic aneurysm formation by targeting the miR-4688/TULP3 axis." (PMID 33546665, 2021).
ciliopathies (3 papers, 2022 to 2025). "We now focused on the effects of Tulp3 depletion on potential ciliopathy-associated phenotypes during zebrafish embryogenesis." (PMID 40940409, 2025). "Tulp3 deficiency resulted in well-known ciliopathy-associated phenotypes including pronephric cysts, body curvature and altered left-right asymmetry." (PMID 40940409, 2025). "TMEM67 and TULP3-associated ciliopathies were frequently associated with ARFI-based liver fibrosis which is in line with previous reports." (PMID 40247009, 2025). "Only recently, TULP3-associated ciliopathy was described with an obligate liver involvement." (PMID 40247009, 2025). "We show that the knockdown of Tulp3 resulted in well-known ciliopathy-related phenotypes as well as defective ciliogenesis during zebrafish embryogenesis." (PMID 40940409, 2025).
liver fibrosis (3 papers, 2022 to 2025). "We now aimed to study whether signs of liver fibrosis are already detectable during zebrafish embryogenesis upon loss of Tulp3." (PMID 40940409, 2025). "Furthermore, we demonstrate that loss of Tulp3 causes upregulation of genes related to liver fibrosis." (PMID 40940409, 2025). "We also examined if signs of liver fibrosis are already detectable in Tulp3 deficient embryos." (PMID 40940409, 2025).
pancreatic ductal adenocarcinoma (3 papers, 2019 to 2025). An infiltrating adenocarcinoma that arises from the epithelial cells of the pancreas. "The function of TULP3 was identified as a transcription factor and a primary regulator of carcinogenesis in pancreatic ductal adenocarcinoma." (PMID 40141211, 2025). "Previously, the TULP3 transcription factor was identified as a possible prognostic biomarker in pancreatic ductal adenocarcinoma." (PMID 30640939, 2019).
cyst (2 papers, 2022 to 2024). A sac-like closed membranous structure that may be empty or contain fluid or amorphous material. "Cyst growth was also suppressed in adult models of ADPKD following inactivation of Tulp3, which affects the membrane associated protein composition of cilia without dismantling the organelle entirely." (PMID 38693102, 2024). "Conditional knockout (cko) of Tulp3 in renal tubules in mice using Ksp1-Cre or HoxB7-Cre caused cyst formation during development approximating ciliary loss." (PMID 35832738, 2022). "Recent genetic studies of Tulp3 provided compelling evidence for cilia-localized signals in determining cyst growth." (PMID 35832738, 2022). "Residual activity of cCDCA is likely sufficient to drive considerable cyst growth that is rapidly ongoing, thus preventing a rescue of cyst growth in the Tulp3-Pkd1 double cko during development." (PMID 35832738, 2022). "The Pkd1 cko late-onset model offers a cyst suppressor system to test the cCDCA candidates from among the TULP3/IFT-A ciliary cargoes." (PMID 35832738, 2022). "Therefore, it is highly likely that TULP3 traffics cilia-localized cyst inhibition (CLCI) signal(s) during kidney development." (PMID 35832738, 2022). "This genetic epistasis between Tulp3 and Pkd1 implied that some TULP3 ciliary cargoes suppress cystogenesis independently of polycystins during kidney development and that dysregulation of these signals may significantly contribute to the cyst growth in ADPKD." (PMID 35832738, 2022). "Recent studies of the tubby family protein, Tubby-like protein 3 (TULP3), have provided new insights into the cilia-localized mechanisms that determine cyst growth." (PMID 35832738, 2022). "Recent studies of Tulp3 mouse models have indicated complex counterregulatory cilia localized signals that positively (cCDCA) and negatively (CLCI) impact cyst growth." (PMID 35832738, 2022). "If TULP3/IFT-A can traffic the components for both CLCI and cCDCA signals to cilia in the absence of polycystins, why does concomitant Tulp3 cko result in such different effects on cyst growth following early and late Pkd1 gene inactivation?" (PMID 35832738, 2022). "Glis2 and PC2 protein expression in Pkd1;Tulp3 double knockout cells remained unchanged from non-knockout controls further supporting the strict correlation of Glis2 levels in vitro with polycystin-dependent cyst forming potential in vivo." (PMID 38693102, 2024). "Alternatively, Tulp3 could additionally regulate a cCDCA signal during development, but fast cyst progression in absence of Pkd1 could make such regulation difficult to detect." (PMID 35832738, 2022). "Based on available data from TULP3/IFT-A-mediated differential regulation of cystogenesis in kidneys with deletion of polycystins either during development or in adulthood, we hypothesize the existence of cilia-localized components of CDCA (cCDCA) and cilia-localized cyst inhibition (CLCI) signals." (PMID 35832738, 2022). "Therefore, TULP3 may regulate cCDCA in addition to the CLCI during development, but fast cyst progression in absence of Pkd1 could make such regulation difficult to detect." (PMID 35832738, 2022).
fibrocystic disease (2 papers, 2022). "Patient variants in Tubby Like Protein-3 (TULP3) have recently been associated with progressive fibrocystic disease in tissues and organs." (PMID 36276950, 2022). "Therefore, a mutation in the Tubby domain of TULP3 may result in fibrocystic disease in patients by disrupting the transport of multiple signaling proteins regulated by the cilium." (PMID 36276950, 2022). "The mechanisms by which mutations in TULP3 drive hepatorenal fibrocystic disease are not understood." (PMID 36276950, 2022).
hepatic disease (2 papers, 2022 to 2025). "And liver disease is usually the earliest to appear in individuals carrying a double allelic variant in the TULP3 gene." (PMID 40282234, 2025). "Taken together, these results indicated that the R382W TULP3 variant identified in patients with fibrocystic renal and hepatic disease caused a loss of function of TULP3 by disrupting protein transport to the primary cilium." (PMID 36276950, 2022). "Here we present two sisters with inherited fibrocystic kidney and liver disease attributable to a rare homozygous mutation in the ciliary protein TULP3." (PMID 36276950, 2022). "Here we report two sisters from consanguineous parents with fibrocystic renal and hepatic disease harboring a homozygous missense mutation in TULP3 (NM_003324.5: c.1144C>T, p.Arg382Trp)." (PMID 36276950, 2022). "Here we present two sibling patients from a consanguineous Iranian family presenting with fibrocystic renal and hepatic disease and harboring a homozygous R382W TULP3 mutation." (PMID 36276950, 2022). "In sum, we identified a missense mutation in the gene TULP3 by WES in two Iranian sisters from a consanguineous family presenting with fibrocystic renal and hepatic disease." (PMID 36276950, 2022).
hypertrophic cardiomyopathy (2 papers, 2022). A condition in which the myocardium is hypertrophied without an obvious cause. "Hypertrophic cardiomyopathy in the 6th and 7th decade of life has also been associated with TULP3 patient variants." (PMID 36276950, 2022). "Altogether, we describe compelling clinical and experimental data to substantiate variants in TULP3 as a monogenic cause of progressive degenerative liver fibrosis with variable fibrocystic kidney disease and hypertrophic cardiomyopathy." (PMID 35397207, 2022). "TULP3-affected individuals develop hypertrophic cardiomyopathy that appears to be age related." (PMID 35397207, 2022).
Joubert syndrome (2 papers, 2022). Joubert syndrome (JS) is characterized by congenital malformation of the brainstem and agenesis or hypoplasia of the cerebellar vermis leading to an abnormal respiratory pattern, nystagmus, hypotonia, ataxia, and delay in achieving motor milestones. "We first tested the ability of R382W TULP3 to facilitate the ciliary transport of Arl13b, a small G-protein associated with Joubert’s Syndrome that requires Tulp3 for transport into the cilium in kidney cells." (PMID 36276950, 2022). "Furthermore, we reveal that some Joubert syndrome mutations perturb INPP5E ciliary targeting, and clarify how each CLS works: (i) CLS4 recruits PDE6D, RPGR and ARL13B, (ii) CLS2-CLS3 regulate association to TULP3, ARL13B, and CEP164, and (iii) CLS1 and CLS4 cooperate in ATG16L1 binding." (PMID 36063381, 2022).
polycystic kidneys (2 papers, 2021 to 2025). "Here, we present the protein–protein interaction network of TULP3, a protein that is responsible for the trafficking of G-protein-coupled receptors to cilia and whose aberrant expression is associated with severe developmental disorders and polycystic kidney disease." (PMID 33187986, 2021). "TULP3-IFT-A is also responsible for the ciliary transport of other integral membrane proteins such as the Polycistin 1/2 complex, which is implicated in polycystic kidney disease (PKD)." (PMID 33187986, 2021). "Indeed, mice with kidney-specific Tulp3 knockout showed a lack of ciliary PC2 to polycystic kidneys." (PMID 39900437, 2025).
rectal adenocarcinomas (2 papers, 2019 to 2021). "Another study also showed that high expression of TULP3 was associated with lymphatic and vascular invasion in colon and rectal adenocarcinomas." (PMID 34874810, 2021). "In addition, higher TULP3 gene expression was associated to lymphatic and vascular invasion in colon adenocarcinoma (COAD) and rectum adenocarcinoma (READ), respectively." (PMID 30640939, 2019).
spina bifida (2 papers, 2018 to 2024). A congenital neural tube defect in which vertebrae are not fully formed. "In line with a role of TULP3 in trafficking multiple cargoes to cilia, TULP3 has been implicated in neural tube patterning, renal and liver cystogenesis, adipogenesis, and spina bifida." (PMID 38864436, 2024).
anencephaly (1 paper, 2022). A rare neural tube defect during pregnancy, resulting in the absence of a large portion of the brain and skull in the fetus. "The results did not support the association of a heterozygous R382W variant in TULP3 with anencephaly." (PMID 36276950, 2022).
colon cancer (1 paper, 2018). "One of the identified genes, TULP3, an inhibitor of hedgehog signaling caught our attention, as CIN had been reported to be transcriptionally altered in response to inhibition of hedgehog signaling in colon cancer cells." (PMID 29724193, 2018).
developmental delay (1 paper, 2021). "We found that TULP3 knockdown mimicked C646 treatment, resulting in developmental delay in a large percentage of the population." (PMID 33187986, 2021).
endometrial carcinoma (1 paper, 2021). A malignant tumor arising from the epithelium that lines the cavity of the uterine body. "In fact, we queried the COSMIC (the Catalog of Somatic Mutations In Cancer) database for mutations in TULP3 associated with cancer and identified with cancer and identified K320R, a mutation associated with endometrial carcinoma, which corresponds to a site of acetylation that we identified." (PMID 33187986, 2021).
gastric cancer (1 paper, 2025). A primary or metastatic malignant neoplasm involving the stomach. "Existing studies indicate that TULP3 silencing inhibits the proliferation, migration, and invasion of gastric cancer cells via the PTEN/Akt/Snail pathway." (PMID 40282234, 2025).
glioma (1 paper, 2022). A benign or malignant brain and spinal cord tumor that arises from glial cells (astrocytes, oligodendrocytes, ependymal cells). "RNA-seq results also revealed that alteration of TULP3 was common to all examined EN1 KD glioma cell lines." (PMID 35163043, 2022).
hypospadias (1 paper, 2020). Hypospadias is the displacement of the urethral meatus on the ventrum of the penis. "We also identified cg25196688 and expression of TULP3 (TUB like protein 3) as causally related to hypospadias." (PMID 32728162, 2020).
nonsmall-cell lung cancer (1 paper, 2021). "MicroRNA-506 (miR-506), a miRNA, has been proven to act as a tumor suppressor gene in nonsmall-cell lung cancer (NSCLC); Tubby-like protein 3 (TULP3) is a potential target gene of miR-506." (PMID 34874810, 2021).
Obesity (1 paper, 2025). Accumulation of substantial excess body fat. "Mutations in the TUB gene can lead to obesity, and TULP3 is the family member most closely related to TUB, so we speculate that it may also have something to do with obesity formation." (PMID 40282234, 2025). "The results of this study are useful for revealing the role of TULP3 in influencing lipid differentiation and provide a molecular basis for the treatment of obesity diseases, as well as the improvement of livestock and poultry meat quality." (PMID 40282234, 2025). "In addition, it has been reported that TULP3 plays a regulatory role in the functioning of primary cilia, which play an important role in directing the expansion of white adipose tissue during obesity." (PMID 40282234, 2025).
retinitis pigmentosa (1 paper, 2021). Retinitis pigmentosa (RP) is an inherited retinal dystrophy leading to progressive loss of the photoreceptors and retinal pigment epithelium and resulting in blindness usually after several decades. "Dysregulation of TULPs has been implicated in a number of human diseases including retinitis pigmentosa (TULP1 and TULP2), PKD (TULP3), and several cancers (TULP3)." (PMID 33187986, 2021).
scoliosis (1 paper, 2025). A congenital or acquired spinal deformity characterized by lateral curvature of the spine. "We also observed scoliosis in a significant number of adult Tulp3 knockout zebrafish." (PMID 40940409, 2025).
cancer (4 papers, 2018 to 2025). A tumor composed of atypical neoplastic, often pleomorphic cells that invade other tissues. "TULP3 is the family member most closely related to TUB, and it is highly expressed in adipose tissue and is known to promote cancer development, embryonic development, and neurodevelopment." (PMID 40282234, 2025). "Conversely, we demonstrated that only the CROCC-associated signature, which included the DNA homologous recombination factor RAD52, the tumour suppressor gene HIC1 and the repressor of the sonic hedgehog pathway TULP3, had a prognostic value in ER-negative/HER2-negative cancers." (PMID 29559730, 2018).
kidney disease (4 papers, 2022 to 2025). "Therefore, our data demonstrates that the Tulp3 loss of function zebrafish model represents a suitable disease model to study progressive fibrocystic liver and kidney disease." (PMID 40940409, 2025). "TULP3 gene variants cause progressive liver and kidney disease." (PMID 40282234, 2025). "The progressive course of TULP3-dependent fibrocystic liver and kidney disease emphasizes that, for the identification of potential targets for therapeutic actions to circumvent or delay organ dysfunction, a detailed understanding of the disease mechanism is very important." (PMID 40940409, 2025).
tumor (3 papers, 2019 to 2025). "In this study, in vitro cell assays and in vivo tumor generation assays were conducted to validate the functions of miR-506 and its downstream target gene TULP3." (PMID 34874810, 2021). "In all of them, we observed a statistically significant increase in TULP3 expression levels in colorectal samples compared to NT samples, despite the small number compared to tumour samples." (PMID 30640939, 2019). "In the TCGA COAD and READ studies, we observed higher fold-changes of TULP3 gene expression in tumour samples relative to NT samples (logFC = 0.804 and logFC = 0.590, respectively)." (PMID 30640939, 2019). "In vivo tumor formation experiments also exhibited consistent results indicating that the functions of TULP3 might be correlated with the promotion of tumorigenesis." (PMID 34874810, 2021). "miR-506 suppresses Non-Small Cell Lung Cancer (NSCLC) progression by regulating Tubby-like protein 3 (TULP3), inducing mitochondrial apoptosis, and in vivo studies confirm its ability to reduce tumor growth, highlighting its role in NSCLC therapy." (PMID 40248198, 2025). "It was found that miR-506 acts as a tumor suppressor that can inhibit cell viability and induce cell mitochondrial apoptosis of NSCLC by regulating TULP3." (PMID 34874810, 2021).
degenerative disease (2 papers, 2022 to 2025). "In humans, bi-allelic deleterious variants in TULP3 are the cause of a progressive degenerative disease affecting the liver, kidney and heart tissue." (PMID 40940409, 2025).
heart disease (2 papers, 2022 to 2025). "Recently, we and others have shown that individuals carrying pathogenic TULP3 variants suffer from progressive liver, kidney and heart disease." (PMID 40940409, 2025).
TULP3 also shares sentences with these, for which no sentence is quoted: Kidney Cyst (3 papers); cystic kidney (2); autoimmune disease (1); breast carcinoma (1); cardiomyopathy (1); colon adenocarcinoma (1); colon polyps (1); fibrosis (1); gastric tumor (1); glioblastoma multiforme (1); Hepatic steatosis (1); metabolic disorders (1); neuroblastoma (1); pancreatic cancer (1); steatosis (1).